RNU6-121P (RNA, U6 small nuclear 121, pseudogene)
Gene: Small nuclear RNA gene on chromosome 1 (154,297,650 to 154,297,748, forward strand). Ensembl gene ENSG00000222457.
Homologues: Orthologues: chimpanzee U6 (97% identical), dog U6 (66% identical). Paralogues in human: RNU6-239P (94% identical), RNU6-1263P (82% identical), RNU6-247P (82% identical), RNU6-41P (82% identical), RNU6-1122P (81% identical), RNU6-38P (81% identical), RNU6-393P (81% identical), RNU6-574P (81% identical), RNU6-618P (81% identical), RNU6-820P (81% identical), RNU6-1060P (80% identical), RNU6-1075P (80% identical), and 1287 more.